MYC (MYC proto-oncogene, bHLH transcription factor)
Diseases named in the same sentence as MYC in open-access papers (continued):
Sharing a sentence is not in itself a finding about the gene and the disease.
cancer (continued). "MYC is often overexpressed in cancer, and in many cases, this overexpression arises from either genomic translocation or amplification, which occur in at least 9–28% of all human cancers." (PMID 37639465, 2023). "We found in our cancer cell modes that when MYC was activated, increased expression of glycosylated 4F2hc was detected in all three cell lines, and oscillation of 4F2hc was lost in SKNAS." (PMID 37639465, 2023). "It is well known that MYC is a highly preserved oncogenic transcriptional factor that is overexpressed in various cancers and controls oncogenic behavior like increased cell differentiation, proliferation, metastasis, and apoptosis evasion." (PMID 37174125, 2023). "4E-BP1 is a master regulator of protein synthesis control, required for cancer cell survival in MYC-dependent tumorigenesis." (PMID 36969025, 2023). "An in-depth analysis of SKA family genes confirmed that the SKA score was positively related to some cell cycle pathways and DNA replication in pan-cancer, including E2F targets, G2M checkpoint, MYC targets V1/V2, mitotic spindle and DNA repair." (PMID 37180139, 2023). "c-Myc is an oncogene that is aberrantly expressed, e.g., from MYC amplification and chromosomal translocation, in the majority (> 70%) of human cancers." (PMID 37828578, 2023). "Cancer cells also maintain Ser62 phosphorylation of c-MYC by downregulating protein phosphatase 2A (PP2A), a p-Ser62 targeting phosphatase." (PMID 36765581, 2023). "Previous studies have reported that BET inhibition blocks expression of certain key oncogenes, such as c-MYC in many cancers." (PMID 36733715, 2023). "Mounting studies have proven that the amplification of MYC mapped to 8q24.21 is the major measure to prompt MYC overexpression and is regularly examined in aggressive cancers including UC with metastasis and unfavorable survival outcome." (PMID 36776299, 2023). "Most hematological malignancies are characterized by overexpression of certain cancer promoting genes, such as MYC, MCL1 and cyclin D1." (PMID 37552223, 2023). "Since directly targeting MYC with small molecules and siRNA is difficult, reshaping the regulators of MYC signaling pathways to indirectly control MYC has become a new strategy for cancer treatments." (PMID 36765885, 2023). "Maintaining MYC at a steady-state level is crucial for normal cell function, and its overexpression leads to many cancers." (PMID 37446009, 2023). "In this context, Omomyc is the first clinical-stage cell-penetrating peptide targeting MYC for cancer treatment." (PMID 36765784, 2023). "Our findings, in sum, indicate that overexpressed MYC suppresses circadian oscillation of transcriptional and metabolic programs across multiple models of cancer." (PMID 37639465, 2023). "The oncogene MYC is frequently amplified and is considered a downstream effector of various oncogenic signaling pathways in human cancers." (PMID 37759234, 2023). "The kidney isoform of GLS (GLS1) is regulated by the oncogene MYC and we have shown that its activity and downstream Krebs cycle-independent pathways is crucial to cancer cell survival and proliferation." (PMID 37512481, 2023). "On the positive side, it stimulates the p15Ink4b pathway, raises oxidative phosphorylation, and elevates KDM5A/MYC protein expression, resulting in increased cancer cell proliferation." (PMID 36975603, 2023). "For the context-depend on partners of p-TEFb including NF-kB in many types of cancer cells, SOX2 and SOX10 in Schwann cells, Mediator both in serval cancer cells and pluripotent stem cells, and c-MYC in pluripotent stem cells." (PMID 36875763, 2023). "As targeting MYC has been shown to be very difficult with small molecules, promoting MYC degradation can provide a fine strategy for cancer treatments via CSC suppression." (PMID 36765885, 2023). "The lower level of Trp in CRC patients’ plasma probably related to the enhanced uptake of Trp by cancer cell, which was drove by proto-oncogene MYC gene." (PMID 37978537, 2023).
cancer (continued). "Additional pan-cancer bioinformatic analyses show hnRNP H expression to be anticorrelated with MYC hallmarks, consistent with the reduced splicing of the HRAS exon in MYC-driven cancer." (PMID 37399401, 2023). "Reduced MYC expression was found in cancer cells localized in the area distant from blood vessels where TME contains limited levels of oxygen and glucose." (PMID 37869102, 2023). "The pharmacological inhibition of the PI3K/AKT/mTOR pathway significantly reduces MYC levels and demonstrates therapeutic efficacy in MYC-driven cancers." (PMID 37755397, 2023). "When switching to a paclitaxel-free culture environment, the cells with decreased levels of SOX1 re-express MYC, resulting in increased abundance of proliferative cancer cells." (PMID 37369660, 2023). "This review paper aims to provide an overview and discussion of the intricate mechanisms through which MYC influences tumorigenesis and therapeutic resistance in cancer." (PMID 37755397, 2023). "Over 20% of basal cancers in TCGA and 35% of basal cancers in METABRIC have amplifications of the SCRIB locus, consistently with the higher prevalence of MYC oncogene amplifications in these cancers." (PMID 36675340, 2023). "Given the importance of MYC in cancer progression, it has long been recognized as a drug target despite the infeasibility of targeting Myc." (PMID 37460542, 2023). "Pan-cancer analysis shows that MYC is one of the most frequently deregulated oncogenes in humans and is a major driver of tumorigenesis and is associated with an unfavorable prognosis." (PMID 37443779, 2023). "Recent progress on characterizing the protein interactome of MYC has shed new lights on understanding the function of MYC and further expands the role of MYC function in cancer." (PMID 37601651, 2023). "As a proto-oncogene, MYCN is frequently deregulated in human cancers, and MYC-dependent metabolic reprogramming is critical for tumorigenesis." (PMID 37190157, 2023). "Despite the importance of MYC for embryonic and cancer growth, several studies have shown that MYC is largely dispensable for normal tissue growth and homeostasis in juvenile and adult stages." (PMID 37731815, 2023). "To validate the results of the screen and confirm robustness of our approach for identification of MYC‐dependent vulnerabilities in cancer cells, we focused on the top 10 most significantly depleted E‐boxes in K562 cells." (PMID 37519063, 2023). "On the other hand, the lncRNA PANDA (p21-associated noncoding RNA DNA damage-activated) inhibits the expression of the oncogene MYC and promotes the expression of the tumor suppressor p21, thereby inhibiting cancer cell proliferation." (PMID 37232821, 2023). "Several studies have reported a significant correlation between high MYC V1 and V2 scores, worse survival, and cancer aggressiveness." (PMID 36982953, 2023). "Oncogenic MYC contributes to the genesis of many human cancers, which strictly depends on its partner Max to regulate gene transcription." (PMID 37345307, 2023). "Accordingly, HIF1α and MYC-dependent genes were differentially expressed between dormant and proliferating cancer cell samples." (PMID 37456245, 2023). "TRIP12 plays an important role in Z363‐induced cancer cell apoptosis by directly and indirectly inhibiting MYC activity." (PMID 36639831, 2023). "Consistent with our study’s drug response associations, therapeutic approaches for bromodomain inhibition in cancers characterized by MYC activation are being explored." (PMID 36731467, 2023). "MYC is a master regulator of cell proliferation and metabolism and is central to the pathogenesis of many human cancers." (PMID 38239638, 2023). "MYC has a large protein network and is likely to promote cancer development in a spatial and concentration-dependent manner, depending on the global or relative level of target genes." (PMID 37443779, 2023).
cancer (continued). "Our results also highlight a transcriptomic trajectory from proliferative to inflammatory/MYC transcriptomic states in resistant cancers." (PMID 38084922, 2023). "As mentioned in the Introduction above, MYC remains one the most attractive oncoprotein remaining to be exploited for therapeutic value in cancer patients." (PMID 37233863, 2023). "For the nuclear DAMPs subtype, GSEA revealed that expression of cancer hallmarks of MYC targets, NOTCH signaling, TGF-β signaling, unfolded protein response (UPR), MTORC1 signaling, and IL-8 production was higher in the nuclear DAMPs subtype." (PMID 37033966, 2023). "The results from the “GTBAdb” database suggested that high USP45 expressing activated the cancer signaling, including MYC pathways." (PMID 36765885, 2023). "MYC gene is one of the most frequently deregulated driver genes in human cancer and usually acts as a potential anticancer target." (PMID 37280589, 2023). "These pathways, such as the PI3K/Akt/mTOR, AMPK, Wnt/β-Catenin, HIF, NF-κB, or MYC pathway, are often dysregulated, resulting in metabolic alterations that facilitate the growth and survival of cancer cells." (PMID 38002335, 2023). "Targeting MYC in cancer cells with high genomic instability can induce cell death and enhance vulnerability to DNA-damaging agents." (PMID 37755397, 2023). "The oncogene MYC is deregulated in various human cancers and drives several cancer-related hallmarks." (PMID 37570631, 2023). "Using time-series RNA-sequencing and metabolomics in three distinct cancer cell lines, we demonstrated that MYC upregulation in cancer cells disrupted over 85% of oscillating genes." (PMID 37639465, 2023). "By targeting WDR5, it is possible to disrupt the activation of MYC and potentially limit cancer progression." (PMID 37568727, 2023). "Since over-expression of MYC in cancer cells exposes them to higher vulnerability to splicing inhibition, we set out to investigate the cytotoxicity of drugs that affect different steps of the splicing process." (PMID 37599362, 2023). "Further, USP45 overexpressing can upregulate MYC, and this overexpressing can significantly enhance cancer development, cancer cell stemness and drug resistance." (PMID 36765885, 2023). "Since then, MYC is found to be one of the most dysregulated, usually over-activated, oncogenic gene in human cancers." (PMID 37601651, 2023). "Similar to MYC, which is often over-expressed in human cancer, CDCA7 is also over-expressed in several human cancers." (PMID 37510310, 2023). "The transcription factor MYC is a proto-oncogene that can maintain several processes of cancer metabolism and plays an important role in regulating cancer genes related to glucose metabolism Its family members are mainly divided into C-MYC, N-MYC, and L-MYC." (PMID 37204526, 2023). "The SKA score was positively related to cell cycle pathways and DNA replication across cancers, such as E2F targets, the G2M checkpoint, MYC targets V1/V2, mitotic spindles and DNA repair." (PMID 37180139, 2023). "This revealed that HIF1α and MYC were significantly repressed in dormant as compared to the proliferating cancer cells." (PMID 37456245, 2023). "MYC is an oncogene that participate in regulation of 20% cancers so it is a hot topic to development drugs targeting MYC and its related pathways." (PMID 36161776, 2023). "Gene set enrichment analysis (GSEA) revealed that multiple cancer signaling hallmarks, including MYC targets, NF-κB signaling, and G2/M checkpoint, were associated with IBN-R and Dual-R MCL cells." (PMID 36719376, 2023).
cancer (continued). "One Crohn-related non-SRC-type SB-PCC harbored a frameshift deletion of the CTNN1A gene, along with KRAS and MYC amplifications, while a CDH1 mutation was identified in another cancer (SRC type, Crohn related)." (PMID 36812376, 2023). "To date, a combined analysis of essential MYC‐bound E‐boxes and their downstream target genes important for growth of different types of cancer is missing." (PMID 37519063, 2023). "Rewired metabolism leads to therapeutic vulnerability in MYC-driven cancers and provides potential drug targets." (PMID 37443779, 2023). "Cancer cell 2 subcluster highly expressed the signature genes of MYC target v1, MYC target v2, and oxidative phosphorylation pathways." (PMID 37998349, 2023). "Across human cancer, MYC is frequently amplified and MYC can mitigate antitumor effects of many cancer therapeutics." (PMID 37642941, 2023). "The four SSOs were selected from a panel of eight SSOs, each targeting a different vulnerability previously identified in MYC‐driven cancers, due to their higher splicing efficiencies." (PMID 36684069, 2023). "MYC addiction is therefore a cancer vulnerability that can be therapeutically exploited through targeting its activity." (PMID 37400551, 2023). "SP1, HIF-1, and MYC are often overexpressed in tumors, which indicates the importance of their roles in the development of cancer." (PMID 37998757, 2023). "MYC also changed the time of the day in which metabolites related to amino acid and nucleotide metabolism peaked in cancer cells." (PMID 37639465, 2023). "Since MYC activity was one of the most well-characterized contributors to the stem cell trait in cancer cells, we acquired the MYC activity score based on the RABIT transcription factor regulatory impact of each sample from the TCGA-BRCA dataset." (PMID 36982338, 2023). "Despite numerous challenges in MYC-related immunotherapy, continuous major breakthroughs in recent years have given scientists unwavering confidence in targeting MYC to treat cancer." (PMID 36966168, 2023). "First, as described in Section 2, all HIF-1, SP1, and MYC are deeply involved in cancer-related cellular mechanisms including metabolism, angiogenesis, anticancer immunity, and regulation of TME." (PMID 37998757, 2023). "Further, indirect downregulation of MYC via ubiquitin–proteasome mechanisms is an excellent strategy for targeting CSCs, for instance activating SCFFBXW7 and inhibiting deubiquitinase USP28 of MYC suppresses cell proliferation in diverse cancer." (PMID 36765885, 2023). "Aberrant miRNA and mRNA expression profiles were detected in different cancer entities and MYC was shown to upregulate, among others, the oncomiR miR-17-92 cluster, whereas an association to the cytogenetic status, especially 1q gains, was not reported." (PMID 37766215, 2023). "The protooncogene c-MYC and its encoded transcription factor protein, c-MYC, are deregulated in many types of cancers." (PMID 37111592, 2023). "Our results showed that genes with a high gain of novel isoforms are associated with cancer-related signatures, such as RNA splicing, TGF pathway, JAK/STAT pathway, and MYC pathway." (PMID 37735421, 2023). "Studies have reported that LncRNA EPIC1 promotes cell cycle progression by interacting with MYC through EPIC1’s 129–283 nt region in Cancer." (PMID 37639158, 2023). "GLUT1 oscillation was not ablated by MYC in any of the cell lines, and it was only upregulated by MYC in SHEP, in contrast to previous reports that MYC transcriptionally upregulates SLC2A1 in other cancer models." (PMID 37639465, 2023). "The transcription factor MYC is a proto‐oncogene with a well‐documented essential role in the pathogenesis and maintenance of several types of cancer." (PMID 37519063, 2023). "The biopolymer is designed to inhibit specific cancer pathways (MYC) and thus has greater specificity to cancer cells and has lesser off-site targets on healthy normal cells." (PMID 37370649, 2023).
cancer (continued). "High levels of MYC and CDK2 were observed in later-stage metastatic cells, prompting the investigation of dinaciclib, a CDK inhibitor known to induce apoptosis in cancer cells with high MYC expression." (PMID 37627192, 2023). "Due to amplifications, mutations, translocations, or posttranslational modifications, MYC is highly expressed in up to 70% of cancers." (PMID 37519063, 2023). "sAJM589 was able to inhibit the transcription of MYC target genes in P493-6 BL cells, as well as to suppress the proliferation of diverse MYC-dependent cancer cell lines and anchorage-independent growth of Raji cells." (PMID 37457123, 2023). "Altogether, we established a unique, well‐validated tool to identify MYC‐regulated target genes relevant for growth of malignant cells, which opens the possibility to gain novel insights into MYC‐dependent vulnerabilities in cancer cells." (PMID 37519063, 2023). "We will discuss below how SOX2, OCT4, KLF4, and c-MYC regulate G1 dynamics in stem cells and cancer cells." (PMID 37760529, 2023). "This compound can also downregulate the transcription of c-MYC in two different cancer cell lines with different translocation break points within the c-MYC (human non-small cell line A549 and human laryngeal epithelial cell line—Hep2)." (PMID 36979947, 2023). "The oncogene MYC, which is frequently altered in human cancers, interferes with the molecular clock." (PMID 37639465, 2023). "LncRNA CCAT1 is closely correlated to c‐MYC transcription and cell growth in a variety of cancer types." (PMID 35650713, 2023). "Further in-depth studies of the RUNX3-MYC relationship will improve our understanding of the interplay between RUNX family members and MYC in cancer biology." (PMID 37400551, 2023). "GSEA in C2 indicated up- and downregulation of gene signatures characteristic for pediatric cancer and MYC/N-driven gene expression." (PMID 37246217, 2023). "Taken together, our results reveal mechanisms by which MYC alters splicing regulation and the phenotype of cancer cells." (PMID 37399401, 2023). "Mutations in the KRAS gene, and protein overexpression of c-MYC (referred to as MYC) and ARF6 are frequent in many types of cancers." (PMID 37158894, 2023). "Deregulated expression of the transcription factor MYC is a crucial event in a wide variety of cancer cells." (PMID 36830948, 2023). "Previous reports indicate that metformin, an AMPK activator down-regulates c-MYC in an AMPK-dependent manner in breast cancer cell lines.There are several other reports highlighting the significance of AMPK in cancer chemoprevention." (PMID 36875093, 2023). "It is interesting that adult cancers with MYC alterations show similar observations in relation to MYC and mitotic stress and that inhibition of apoptosis can similarly impair precancerous lymphoma in Eμ-Myc mice." (PMID 37958555, 2023). "Destabilization of MYC by C.B supplementation suppresses cancer cell proliferation/metastasis, sensitizes 5-FU treatment, and boosts responsiveness of anti-PD1 therapy." (PMID 36941257, 2023). "While MYC has a reputation of being an undruggable target in cancer, several MYC inhibitors have been developed and some of them have proceeded to clinical trials." (PMID 37731815, 2023). "The specific mechanisms that oncogenically activate MYC and alter its functional output in cancer cells remain poorly understood." (PMID 37755397, 2023). "In AML and pancreatic cancer cells, the compensatory upregulation of MYC via the WNT pathway was reported to reduce the responsiveness of the cancer cells to BET inhibitors." (PMID 37049806, 2023).